SPTBN2 (spectrin beta, non-erythrocytic 2)
Description:
Probably plays an important role in neuronal membrane skeleton.
Synonyms: SCA5; GTRAP41; SCAR14
Tractability: Antibody: its Gene Ontology location is reachable by antibodies, with high confidence. PROTAC: ubiquitination databases record sites on it; its protein half-life has been measured.
Gene: Protein-coding gene on chromosome 11 (66,682,496 to 66,744,670, reverse strand). Ensembl gene ENSG00000173898.
Subcellular location: Cytoplasm, cytoskeleton; Cytoplasm, cell cortex
Subcellular location (Human Protein Atlas): Cytosol; Plasma membrane; Vesicles
Pathways (Reactome):
Developmental Biology: Interaction between L1 and Ankyrins; NCAM signaling for neurite out-growth
Immune System: MHC class II antigen presentation
Signal Transduction: RAF/MAP kinase cascade
Vesicle-mediated transport: COPI-mediated anterograde transport
Gene Ontology:
Molecular function: cadherin binding; actin binding; actin filament binding; structural constituent of cytoskeleton; structural constituent of synapse; phospholipid binding; structural constituent of postsynapse
Biological process: vesicle-mediated transport; actin cytoskeleton organization; postsynapse organization; regulation of postsynaptic specialization assembly
Cellular component: cytosol; extracellular region; spectrin; cell junction; cortical actin cytoskeleton; plasma membrane; apical plasma membrane; cell cortex; cytoskeleton; glutamatergic synapse; neuronal cell body; parallel fiber to Purkinje cell synapse; paranodal junction; postsynaptic spectrin-associated cytoskeleton; presynapse
Genetic constraint (gnomAD): Loss-of-function variants: 107 observed, 277.78 expected, observed/expected ratio (o/e) 0.39, 90% interval 0.33 to 0.45. The upper end of that interval is the gene's LOEUF score, 0.45, which puts it in group 2 of 6, group 1 being the genes least tolerant of losing a copy. Missense variants: 2,569 observed, 3,277.3 expected, observed/expected ratio (o/e) 0.78, 90% interval 0.76 to 0.81. Synonymous variants: 1,289 observed, 1,334.2 expected, observed/expected ratio (o/e) 0.97, 90% interval 0.92 to 1.01.
Gene-disease validity (ClinGen):
ClinGen rates the evidence that SPTBN2 causes each of these diseases.
autosomal recessive spinocerebellar ataxia 14 (autosomal recessive): Definitive.
spinocerebellar ataxia type 5 (autosomal dominant): Definitive. Spinocerebellar ataxia type 5 (SCA5) is a rare subtype of autosomal dominant cerebellar ataxia type III (ADCA type III) characterized by the early-onset of cerebellar signs with eye movement abnormalities and a very slow disease progression.
Homologues: Orthologues: chimpanzee SPTBN2 (99% identical), macaque SPTBN2 (99% identical), mouse Sptbn2 (95% identical), guinea pig SPTBN2 (95% identical), rabbit SPTBN2 (95% identical), dog SPTBN2 (94% identical), pig SPTBN2 (94% identical), rat Sptbn2 (93% identical), tropical clawed frog sptbn2 (67% identical), zebrafish sptbn2 (67% identical). Paralogues in human: SPTBN1 (62% identical), SPTB (52% identical), SPTBN4 (48% identical), SPTBN5 (25% identical), SYNE1 (24% identical), DST (24% identical), MACF1 (23% identical), SYNE2 (22% identical), PLEC (18% identical), SPTAN1 (17% identical), DMD (17% identical), UTRN (17% identical), and 24 more.
Diseases named in the same sentence as SPTBN2 in open-access papers:
SPTBN2 is named in the same sentence as 70 diseases in open-access papers, as found by Europe PMC text mining. Sharing a sentence is not in itself a finding about the gene and the disease. The quoted sentences say what the papers report.
Ataxia (25 papers, 2012 to 2025). Ataxia refers to impaired coordination of voluntary muscle movement. "The genetic analyses identified spinocerebellar ataxia (SCA) in six families, ataxia-telangiectasia in three families, ataxia with vitamin E deficiency in one family, ATP1A3-associated ataxia in one family, and SPTBN2-associated ataxia in one family." (PMID 40635703, 2025). "In the 136-gene ataxia panel, as well as in the whole exome, variant NM_006946.4:c.1898G>A (rs759321471) was detected in the patient’s SPTBN2 gene." (PMID 39596509, 2024). "We identified two novel heterozygous variants of SPTBN2 resulting in severe ataxia which further delineated the correlation between the genotype and phenotype of SCA5, and pathogenesis of variants in SPTBN2 should be further researched." (PMID 33797620, 2021). "Other variants in SPTBN2 show cognitive impairment as well as ataxia (spectrin-associated autosomal recessive cerebellar ataxia type 1, SPARCA1)." (PMID 34528024, 2021). "Mutations in SPTBN2 can lead to a form of spinocerebellar ataxia (SCA5), which is characterized by neurodegeneration, progressive locomotor incoordination, dysarthria, and uncoordinated eye movements." (PMID 34745988, 2021). "In this study, we verified two novel heterozygous variants in SPTBN2, c.486C>G p.I162M in a pedigree and c.2648G>T p.R883L in the sporadic patient, both with cerebellar ataxias, dysarthria, and cognitive dysfunction by targeted next-generation sequencing." (PMID 33797620, 2021). "To date, 26 SPTBN2 mutations, distributed along the entire coding region, have been linked to cerebellar ataxia (HGMD® Professional 2020.4; accessed on 19 February 2020)." (PMID 33801522, 2021). "Five cases of SCAR14 have been described all with homozygous mutations within SPTBN2 and congenital onset of ataxia in normal parents." (PMID 31721007, 2020). "All three cases resemble the phenotype of SCAR14, an autosomal recessive ataxia due to homozygous mutations within the SPTBN2 gene." (PMID 31721007, 2020). "A next generation sequencing 98 gene ataxia panel confirmed a c.812C>T p.(Thr271Ile) mutation within the SPTBN2 gene." (PMID 31721007, 2020). "In SCA5, the ataxia is generally a pure adult-onset ataxia whereas recessive mutations in SPTBN2 cause SPARCA1, a more severe childhood ataxia with cognitive impairment." (PMID 23236289, 2012). "The biological function of SPTBN2 was first reported in association with spinocerebellar ataxia." (PMID 34745988, 2021). "Particularly, βIII spectrin (SPTBN2) is specific to Purkinje cells and is involved in a relatively pure late-onset ataxia phenotype." (PMID 36331550, 2023). "Eleven patients showed very early-onset ataxia and CA with cortical hyperintensities caused by mutations in ITPR1, KIF1A, SPTBN2, PLA2G6, PMPCA, and PRDX3." (PMID 36233161, 2022). "In this study, we identified two novel heterozygous variants of SPTBN2 resulting in severe ataxia which further delineated the correlation between the genotype and phenotype of SCA5, and pathogenesis of variants in SPTBN2 should be further researched." (PMID 33797620, 2021). "Currently, most studies have focused on the role of SPTBN2 in neurodegenerative diseases such as ataxia and cognitive impairment." (PMID 34887379, 2021). "Most recognized are ataxias caused by missense, deletions, or truncations in the SPTBN2 gene that encodes beta III spectrin." (PMID 34528024, 2021). "In the nonseizure group, the yield was 44% (4/9), including one with SCN2A with autism, one FBN1 with Marfan syndrome, one DMD with muscle dystrophy, and one SPTBN2 with spinocerebellar ataxia." (PMID 33333793, 2020). "Six of these candidate variants were located in genes related to ataxia phenotype including ATM, GALC, SPTBN2, SYNE1, and TWNK." (PMID 31455392, 2019).
Ataxia (continued). "Heterozygous mutations in the gene encoding β‐III spectrin (SPTBN2) underlie SCA type‐5 whereas homozygous mutations cause spectrin associated autosomal recessive ataxia type‐1 (SPARCA1), an infantile form of ataxia with cognitive impairment." (PMID 26821241, 2016). "We initially performed targeted capture of >100 known ataxia genes (including SPTBN2) in a group of children with unexplained ataxia including patient V3, followed by next generation sequencing." (PMID 23236289, 2012). "After analysis of the canine orthologues of human spinocerebellar ataxia associated genes, we identified a homozygous 8 bp deletion in the β-III spectrin gene, SPTBN2, associated with spinocerebellar type 5 in humans." (PMID 22781464, 2012). "SPTBN2-KO mice exhibit ataxia and progressive degeneration of Purkinje cells in the cerebellum." (PMID 40465750, 2025). "SPTBN2, a candidate gene at the locus of MDD, is involved in the regulation of the glutamate signaling pathway and mutations in this gene result in a class of spinocerebellar ataxia with the feature of neurodegeneration." (PMID 33479212, 2021). "In mice, Sptbn2 targeting recapitulates adult-onset progressive ataxia, but expression of shorter SPTBN2 isoforms or expression of alternative splice variants suggest that ataxia might reflect hypomorphism or neomorphism rather than complete loss of function." (PMID 34557863, 2021). "In contrast, ITPR1, PTPN1, SPTBN2, and WDR81 are known as cerebellar ataxia-related genes, and there is limited evidence of shared mechanisms with epilepsy." (PMID 37645600, 2023).
spinocerebellar ataxia type 5 (20 papers, 2012 to 2025). "A mutation in SPTBN2 causes spinocerebellar ataxias type-5, a human neurodegenerative disorder that is characterized by progressive locomotor incoordination, slurred speech, and uncoordinated eye movements." (PMID 35968508, 2022). "Mutations in the gene encoding β-III spectrin (SPTBN2) lead to autosomal dominant (AD) spinocerebellar ataxia type 5 (SCA5), and spinocerebellar ataxia autosomal recessive type 14 (SCAR14)." (PMID 33801522, 2021). "Spinocerebellar ataxia type 5 (SCA5) is an inherited neurodegenerative disease associated with mutations in the SPTBN2 gene that encodes spectrin." (PMID 32033020, 2020). "The gene encoding beta-III spectrin (SPTBN2) was a particularly strong candidate, as mutations in the gene have been shown to cause spinocerebellar ataxia type 5 (SCA5) in humans as well as an inherited neurological disorder in the dog." (PMID 23741357, 2013). "The SPTBN2 gene encodes for the beta-III spectrin (protein forming part of cytoskeleton), which is expressed mainly in the cerebellum (affecting glutamate turnover) and several mutations have been associated with Spinocerebellar Ataxia Type 5 (SCA5) in humans." (PMID 40465750, 2025). "SPTBN2 mutation can result in spinocerebellar ataxias type-5." (PMID 35968508, 2022). "However, the previous study mainly focused on the effect of SPTBN2 mutation on spinocerebellar ataxias type-5." (PMID 35968508, 2022). "Additionally, SPTBN2 mutations have been identified to cause spinocerebellar ataxia type 5 via a mechanism involving glutamate receptors, setting precedence for mutant spectrin protein to cause neurodegeneration." (PMID 33635380, 2021). "We used NEPTUNE to investigate Sptbn2, mutations in which cause spinocerebellar ataxia type 5." (PMID 34557863, 2021). "Mutations in the gene encoding β-III spectrin (SPTBN2) lead to spinocerebellar ataxia type-5 (SCA5) and spectrin-associated autosomal recessive cerebellar ataxia type-1 (SPARCA1), two human neurodegenerative diseases involving gait ataxia and cerebellar atrophy." (PMID 28173092, 2016). "This study demonstrated that a spontaneous canine model of spinocerebellar ataxia type 5 is caused by a mutation in SPTBN2, the gene encoding β-III spectrin, which offers an invaluable opportunity for further understanding of the disease pathogenesis and treatment." (PMID 22781464, 2012). "Spinocerebellar ataxia type 5 (SCA5) is a neurodegenerative disease caused by mutations in the SPTBN2 gene encoding the cytoskeletal protein β-III-spectrin." (PMID 37626910, 2023). "Spinocerebellar ataxia type 5 (SCA5) is a neurodegenerative disease stemming from autosomal dominant mutations in the SPTBN2 gene encoding the cytoskeletal protein β-III-spectrin." (PMID 37626910, 2023). "Mutations in SPTBN2 give rise to spinocerebellar ataxia type 5 (SCA5, OMIM# 600224), which is characterized by adult-onset and progressive motor incoordination, postural abnormalities and swallowing difficulties." (PMID 31191255, 2019). "Spinocerebellar ataxia type 5 (SCA5) is a human neurodegenerative disease that stems from mutations in the SPTBN2 gene encoding the protein β-III-spectrin." (PMID 26883385, 2016). "Dominant missense or in-frame mutations in SPTBN2 cause spinocerebellar ataxia type 5 (SCA5) a relatively pure cerebellar disorder with little brainstem or spinocerebellar tract involvement." (PMID 25981959, 2015). "Autosomal dominant mutations in SPTBN2 gene encoding β-III-spectrin cause the neurodegenerative disease, spinocerebellar ataxia type 5 (SCA5)." (PMID 36731793, 2023). "SPTBN2, also known as SCA5, regulates glutamate signaling by stabilizing EAAT4, and mutations in SPTBN2 cause spinocerebellar ataxia type 5." (PMID 33875800, 2021). "In 2006, heterozygous mutations of the brain spectrin gene SPTBN2, encoding β-III spectrin, were found to cause Spinocerebellar Ataxia Type 5 (SCA5)." (PMID 23236289, 2012).
spinocerebellar ataxia type 5 (continued). "Heterozygous mutations in SPTBN2, the gene encoding β-III spectrin, cause Spinocerebellar Ataxia Type 5 (SCA5), an adult-onset, slowly progressive, autosomal-dominant pure cerebellar ataxia." (PMID 23236289, 2012). "Heterozygous mutations of the brain spectrin gene SPTBN2, which encodes the protein β‐III‐spectrin, are one cause of spinocerebellar ataxia type 5 (SCA5), an autosomal dominant neurodegenerative disease." (PMID 31386307, 2019).
colorectal cancer (8 papers, 2021 to 2026). A primary or metastatic malignant neoplasm that affects the colon or rectum. "What’s more, SPTBN2 was associated with poor prognosis in patients with colorectal cancer and was highly expressed in patients with distant metastasis, lymph node metastasis, and clinical advanced colorectal cancer, with statistically significant differences." (PMID 34887379, 2021). "pointed out that lncRNA CERS6-AS1 upregulated ceramide and spectrin beta, non-erythrocytic 2 (SPTBN2), thereby promoting the malignant phenotype of colorectal cancer." (PMID 39539540, 2024). "Studies have shown that SPTBN2 is up-regulated in MPNST, colorectal cancer, and ovarian cancer,which was involved in a variety of biological processes related to tumorigenesis." (PMID 34887379, 2021). "The relative expression of miR-15b in colorectal cancer cells was shown to be significantly lower than in normal cells, and spectrin beta, nonerythrocytic 2 (SPTBN2) was identified as a direct target of miR-15b." (PMID 39456841, 2024). "MeRIP-seq and RNA-sequencing revealed four genes, WD- repeat domain 72 (WDR72), spectrin beta, non-erythrocytic 2 (SPTBN2), microrchidia 2 (MORC2), and prostate androgen-regulated mucin-like protein 1 (PARM1), which could predict the prognosis of patients with colorectal cancers." (PMID 36835633, 2023).
Cognitive impairment (5 papers, 2012 to 2023). Abnormal cognition is characterized by deficits in thinking, reasoning, or remembering. "In contrast, autosomal recessive mutations in SPTBN2 cause a congenital ataxia and cognitive impairment with additional mild spasticity in the two families reported to date." (PMID 25981959, 2015). "We identified a homozygous mutation in SPTBN2, which causes a more severe disorder than SCA5, with a developmental cerebellar ataxia, which is present from childhood; in addition there is marked cognitive impairment." (PMID 23236289, 2012). "Here we report the first description of recessive mutations in SPTBN2 in which there is a severe developmental childhood ataxia but also significant cognitive impairment." (PMID 23236289, 2012). "However, since more than one mutation can co-segregate, particularly in consanguineous families, we went on to consider the contribution of the mutation in SPTBN2 to the observed cognitive impairment." (PMID 23236289, 2012). "Using targeted capture and next-generation sequencing, we identified a homozygous stop codon in SPTBN2 in a consanguineous family in which childhood developmental ataxia co-segregates with cognitive impairment." (PMID 23236289, 2012).
ovarian carcinoma (5 papers, 2021 to 2024). A malignant neoplasm originating from the surface ovarian epithelium. "Our results demonstrated that the downregulation of SPTBN2 in ovarian cancer cases would reduce the risk of death when they were enriched in CD4+ T cells (p < 0.05) or dendritic cells (p = 0.067)." (PMID 34179092, 2021). "In ovarian cancer, the upregulation of SPTBN2 has been associated with poor prognosis." (PMID 34957118, 2021). "In recent studies, it has been confirmed that the mRNA and protein levels of SPTBN2 were upregulated in ovarian cancer, and which was involved in a variety of biological processes associated with tumorigenesis and was highly associated with poor prognosis of ovarian cancer." (PMID 34887379, 2021). "Moreover, interaction analysis proved that two hub genes, SPTBN2 and BCL2L1, were highly associated with poor prognosis in ovarian cancer." (PMID 34179092, 2021). "For example, in ovarian cancer cells, Spectrin beta non-erythrocytic 2 (SPTBN2) may promote tumor migration and invasion by inhibiting the expression of focal adhesion-related proteins and downstream signaling pathways via ITGB4." (PMID 39169946, 2024).
endometrial cancer (3 papers, 2021 to 2022). Primary or metastatic malignant neoplasm involving the endometrium (mucous membrane that lines the endometrial cavity). "Through the study on the dysregulation of miRNA, the rationale of aberrant SPTBN2 expression in endometrial cancer was investigated to be examined." (PMID 34887379, 2021). "After performing the database and conducting a series of validation as mentioned, we identified miR-424-5p as an upstream regulator to inhibit SPTBN2 expression in endometrial cancer." (PMID 34887379, 2021). "Overall, there is no doubt that these findings illustrated the oncogenic role of SPTBN2 in endometrial cancer." (PMID 34887379, 2021). "Next, we explored the potential mechanism of highly expressed of SPTBN2 in the promotion of endometrial cancer occurrence and development." (PMID 34887379, 2021). "Our results indicated that SPTBN2 served as an oncogene in endometrial cancer." (PMID 34887379, 2021). "In conclusion, we demonstrated that by acting as a significant target of miR-424-5p, SPTBN2 could interact with CLDN4 to promote endometrial cancer metastasis via PI3K/AKT pathway in EEC." (PMID 34887379, 2021). "In addition, we confirmed that SPTBN2 was a target of miR-424-5p, which plays a tumor suppressor in endometrial cancer." (PMID 34887379, 2021). "The potential mechanism could partly explain the reason for the highly expressed SPTBN2 in the promotion of endometrial cancer occurrence and development." (PMID 34887379, 2021). "However, the expression, function, and molecular mechanism of SPTBN2 in endometrial cancer remain unclear." (PMID 34887379, 2021). "Moreover, we found SPTBN2 could interact with CLDN4 to promote endometrial cancer metastasis via PI3K/AKT pathway." (PMID 34887379, 2021). "To further investigate the molecular mechanisms of SPTBN2 induced tumorigenesis in endometrial cancer, we conducted co-expression analysis with SPTBN2 and obtained the top ten genes with the best positive correlation according to the mRNA expression of SPTBN2 in TCGA datasets." (PMID 34887379, 2021). "In this study, we investigated the expression and the clinical values of SPTBN2 in endometrial cancer, and we mainly explored the biological functions and the potential interaction among miR-424-5p, SPTBN2 and CLDN4, and identified their effects on progression in endometrial cancer." (PMID 34887379, 2021).
epilepsy (3 papers, 2012 to 2023). A brain disorder characterized by episodes of abnormally increased neuronal discharge resulting in transient episodes of sensory or motor neurological dysfunction, or psychic dysfunction. "Alpha-actinin-4 (ACTN4) also belongs to the spectrin superfamily playing complementary roles to SPTBN1 and SPTBN2 and has been implicated in central nervous system (CNS) disorders such as schizophrenia and epilepsy." (PMID 22350622, 2012).